IL6 (interleukin 6)
Diseases named in the same sentence as IL6 in open-access papers (continued):
Sharing a sentence is not in itself a finding about the gene and the disease.
tumor (continued). "Prior studies have also shown that IR, especially high-LET radiation induces a robust SASP characterized by increased secretion of TGFβ1, MMP9, IL-6, and IGFBPs, promoting chronic inflammation and tumor progression." (PMID 41516087, 2025). "Cytokines like “tumor necrosis factor (TNF-α), IL-1 beta (IL-1β), and interleukin-6 (IL-6)” are released into the tumor microenvironment by the inflammasome from necrotic cells." (PMID 41068541, 2025). "Fisher's review summarized IL‐6's antitumor immune effect, which is achieved by influencing lymph node activation and metastasis, as well as immune infiltration in the tumor microenvironment." (PMID 40103267, 2025). "Together with hypoxia, the upregulation of IL-6 expression by the toll-like receptor signaling pathway in tumor cells promotes the inflammatory response of tumors and promotes tumor resistance, proliferation, and invasion." (PMID 40420185, 2025). "IL6 promotes tumor cell proliferation and angiogenesis by regulating the JAK/STAT3 signaling pathway." (PMID 40841364, 2025). "IL6 expression increased over time in spheroid-only, but was significantly stronger in the co-culture model than macrophage-only or spheroid-only populations, suggesting macrophages enhanced IL-6 production by tumour spheroids." (PMID 40420192, 2025). "IL-17 directly induces IL-6, G-CSF, and CXCL1 production, attracting tumor-associated neutrophils and rendering them the dominant immune cell population within the tumor." (PMID 41516132, 2025). "Stimulation with IL-6 can prompt cell proliferation, enhance cell survival, and increase the invasiveness of tumor cells." (PMID 40040705, 2025). "High levels of IL-6 and IL-8 in the innervated niche are generated upon the engagement of the β-ARs on tumor and immune cells by both noradrenaline from local sympathetic nerves and adrenaline from the blood." (PMID 41306965, 2025). "Monocytes and macrophages are actively recruited to the tumor site and differentiate into TAMs upon induction by factors such as IL-6, CCL2, and GM-CSF present in the TME." (PMID 40083697, 2025). "IL-6 has also been reported to be involved in tumor cell invasion, but the human ILC cell lines including SUM44PE have limited ability to invade using conventional assays." (PMID 40597443, 2025). "The high levels of CRP, an acute-phase protein, are indicative of a pro-inflammatory state driven by cytokine release (e.g., interleukin-6), which supports tumor growth, angiogenesis, and immune evasion." (PMID 39859125, 2025). "VEGF enhances tumor vascularization, while IL-6 fosters an inflammatory environment conducive to tumor growth." (PMID 40061935, 2025). "IL-6 also promoted angiogenesis, tumor invasion, and metastasis through the regulation of hypoxia-inducible factor 1α (HIF-1α), matrix metalloproteinases (MMP2, MMP7, MMP9), and vascular endothelial growth factor (VEGF)." (PMID 40160826, 2025). "Further studies have demonstrated that RA-induced inhibition of EMT in tumor cells is mediated through the downregulation of IL-6 and CAFs." (PMID 40427098, 2025). "These OVA-decorated AuNPs inhibited tumor growth by inducing higher levels of inflammatory factors (IL-1β, IL-6, and TNF-α) by activated macrophages." (PMID 40801739, 2025). "Agents such as metformin, statins, COX-2 inhibitors, and hydroxychloroquine target distinct nodes in this network, from lowering IL-6 and PD-L1 to reprogramming myeloid populations and constraining tumor survival pathways." (PMID 41374963, 2025). "In these mice, the tumor weight and size as well as Chil3 and IL-6 mRNA expression in the tumor tissue were the same as in the control." (PMID 40918453, 2025). "Interleukin-6 (IL-6), a pivotal inflammatory mediator, critically modulates the tumor microenvironment, immune evasion, tumor progression, and therapy resistance in NSCLC." (PMID 41500783, 2025).
tumor (continued). "IL-6 overexpression correlates with the immunosuppressive tumor microenvironment in ESCC, and it can be a predictive biomarker in ESCC patients received with PD-1 inhibitors." (PMID 40433391, 2025). "Conversely, the deletion of IL-6 in tumor-bearing mice enhances the anti-tumor activities of effector T cells and inhibits tumor formation in vivo." (PMID 39652104, 2025). "These genetic alterations influence the tumor microenvironment and immune cell infiltration through key signaling pathways such as IL-6/JAK/STAT3, thereby significantly affecting immunotherapy sensitivity." (PMID 40777022, 2025). "This IL6-driven signaling cascade not only contributes to tumor cell growth but also enhances the immune escape mechanisms within the TME, affecting both immune and non-immune cells within OC-TME." (PMID 40427188, 2025). "Using a Matrigel scaffold, IL-6-dependent DS-1 cells served as the tumor xenograft model, and human mesenchymal stem cells (hMSCs) served as a stromal IL-6 feeding-layer, based on their secretory profile." (PMID 38980514, 2025). "IL6 plays a key role in tumor–immune cell communication, immune cell polarization, and the establishment of a chronic inflammatory microenvironment facilitating metastasis." (PMID 41514627, 2025). "The tumor-promoting action of MSCs can be ascribed to their ability to enhance the stemness qualities of OS cells through the action of IL-6, which promotes tumor growth." (PMID 40149640, 2025). "Western blotting findings confirmed that the mice in the MCPIP1 knockdown group had higher levels of P‐STAT3, P‐JAK2, and IL6 in their tumor tissues than in those of the control group." (PMID 40874680, 2025). "Several inflammatory mediators, including pro‐inflammatory ILs (IL‐1 and IL‐6), are involved in tumor growth, survival, prevention of apoptosis, progression to metastasis, and resistance to drug therapy." (PMID 40088136, 2025). "IL-17 pathway activation promotes differentiation and recruitment of Th17 cells, thereby sustaining chronic inflammation and perpetuating pro-inflammatory cytokine networks (including IL-6, IL-8, GM-CSF), which create a tumour-supportive microenvironment." (PMID 41567225, 2025). "These interrelated events synergize to stimulate osteoclast differentiation, trigger bone resorption, and facilitate the release of TNF and IL-6, thereby promoting tumor metastasis." (PMID 39816691, 2025). "Increased NOS2-derived NO promotes metastasis, where higher clustering of NOS2+ tumor cells leads to increased oncogenic pathway signaling and immune-modulatory proteins, including IL-1, IL-6, IL-8, and TNF-α." (PMID 40663402, 2025). "IL‐6 expression in the spleen differed by sex: in females, only KL tumours bearing mice showed IL‐6 upregulation, whereas in males, K tumours bearing mice showed IL‐6 upregulation." (PMID 40702652, 2025). "We also observed that both GDF15 and log-transformed IL-6 concentration values positively and linearly correlated with tumor weight." (PMID 40124481, 2025). "By secreting chemokines (e.g. CXCL-1) and interleukins (e.g. IL-6), CAFs contribute to an inhibitory immune microenvironment of the pancreas and promote pancreatic cancer tumor growth." (PMID 40259388, 2025). "In myeloid-specific CUL4B KO knockout models, augmented tumor growth and metastasis correlate with elevated IL-6 secretion by MDSCs." (PMID 40230836, 2025). "TNF-α initiates a pro-tumor program in breast cancer cells, increasing proliferation and IL-6/IL-8 and VEGF production in these cells." (PMID 41584509, 2025). "This triggers the release of inflammatory molecules like IL-6 and IL-8 (a cytokine responsible for neutrophil chemotaxis), which transduces signaling mechanisms for tumor development." (PMID 41376623, 2025). "IL-6 contributes to the accumulation of tumor-infiltrating lymphocytes and regulates neutrophil survival, activation, and function via the IL-6/STAT3/PD-L1 signaling axis." (PMID 40313969, 2025).
tumor (continued). "Several other angiogenic factors, except the most studied VEGF, are associated with tumor development, growth, and invasion, such as HGF, angiopoietin-2, IL-6, and TGF-β1." (PMID 41369383, 2025). "While IFN-α has known anti-tumor effects and is used therapeutically in MM, IL-6 plays a dual role, both supporting tumor growth and stimulating T cell activity." (PMID 40948764, 2025). "A particularly noteworthy aspect of IL-6 is its production by cancer cells, suggesting an autocrine role in tumor growth." (PMID 40149421, 2025). "IL-6 is a multifunctional cytokine that is produced by many cell types like tumor cells, immune cells, and smooth muscles that play important roles during inflammation and immune responses." (PMID 40746594, 2025). "Intriguingly, our RNA-Seq analysis demonstrates that XBP1 regulates the gene expression of multiple components of this pathway, including cell surface receptors for IL-6 in cachectic muscle of KPC tumor-bearing mice." (PMID 40655023, 2025). "In bone metastases, tumor‐derived IL‐6 stimulates osteoclast activity, increasing bone resorption and creating a favorable environment for tumor cell colonization and growth." (PMID 40040540, 2025). "IL-6 acts on tumor cells to induce STAT3 target genes that promote proliferation and survival, creating a feedforward autocrine loop." (PMID 40868199, 2025). "Tumor-derived factors such as interleukin-6 (IL-6), tumor necrosis factor-alpha (TNF-α), and granulocyte colony-stimulating factor (G-CSF) stimulate neutrophil proliferation and activation." (PMID 41180708, 2025). "The fibrotic microenvironment rich in IL6+CAFs was associated with decreased high intratumoral CD8+ and CD4+TILs, which normally exert an anti-tumor effect, and was hence correlated with a poorer prognosis." (PMID 40227764, 2025). "CCL26 induces TAMs infiltration and increases the expression of IL-6 and IL-8 in tumor cells, which promotes EMT." (PMID 40034694, 2025). "Tumor cells release cytokines like IL‐6, CRP, and TNF‐α, as well as chemokines, angiogenic factors, and growth factors, inducing inflammatory responses that can promote or inhibit tumor growth." (PMID 40387308, 2025). "Local inflammation induces the activation of interleukin-6 (IL-6) and the proliferation of intestinal epithelial cells resulting in tumor formation." (PMID 41301452, 2025). "Under dual stress-pathogen exposure, we observed the expansion of myeloid-derived suppressor cells (MDSCs) in spleen and the upregulation of IL-6 in colonic mucosa, which facilitated MDSCs recruitment to tumor sites." (PMID 40969768, 2025). "The co-occurrence of ARID1A loss and PIK3CA activating mutations appears to be necessary for tumor development and is known to promote the onset of CCOC via sustained IL-6 production." (PMID 41465243, 2025). "CAFs are known to influence tumor cell behavior through pathways such as those elicited by e.g. IL-6, HGF/MET, IFNβ1 and certain microRNAs." (PMID 40042717, 2025). "CAFs also attract Treg-cells and decrease CD8+ T cell infiltration into TME by secreting TGF-β and IL-6, likely interfering with anti-tumor immunity." (PMID 40092980, 2025). "In a different study investigating a murine breast cancer model, mice that performed continuous endurance exercise exhibited lower tumor volume and decreased levels of IL-6 and vascular endothelial growth factor (VEGF) compared to a control group." (PMID 40362215, 2025). "This suppression of NF-κB activity directly translates into reduced expression of pro-inflammatory cytokines such as TNF-α, IL-6, and IL-1β, which are fundamental for tumor progression, angiogenesis, and immunosuppression." (PMID 41302515, 2025). "TNBC tumor cells secrete several factors, including macrophage colony-stimulating factors (M-CSF) and IL-6, which drive macrophages toward M2 polarization." (PMID 40141437, 2025).
tumor (continued). "In contrast to the previous experiment started at 8 weeks of age to study tumor progression, the alterations in myeloid and T cell populations were accompanied by a significant decrease in IL-6 and IL-4 serum levels in OGP-treated mice." (PMID 40307509, 2025). "Following combined IL-6 blockade, tumors exhibited improved responses to anti-PD-L1 therapy, leading to higher life periods and lower tumor sizes in mice." (PMID 40433391, 2025). "Tumor-associated inflammation, characterized by elevated TNF-α, IL-6, and IL-1β, was effectively suppressed in both colon tissue and systemic circulation." (PMID 41199821, 2025). "Under the distinctive pathophysiological conditions of the TME, cancer-associated inflammatory cytokines, including TNF-α, TGF-β, IFN-I, IL-1, IL-6, and IL-10, often exhibit upregulated expression, thereby modulating the biological behaviors of tumor cells." (PMID 40563367, 2025). "Treated tumor-bearing mice exhibited lowered IL-6 and TNF-α levels and near-normal liver and kidney function, whereas free doxorubicin caused significant inflammation and organ stress." (PMID 40943339, 2025). "We found significantly higher baseline sBCMA (tumor burden) and Il‐6 (mediator of CRS) serum values in patients with EMD and/or diffuse BM infiltration in PET/CT." (PMID 40519771, 2025). "This administration decreased tumor volume and increased mice survival, where the effect was related to a decrease of tumor angiogenesis and changes in the cytokine profile in blood serum, especially IL-6 which is mainly related to the angiogenesis induction." (PMID 40417456, 2025). "IL-6 promotes tumor growth, immune evasion, and resistance to therapy by activating key oncogenic pathways, including JAK/STAT3 and NF-κB." (PMID 40565133, 2025). "Within the TME, tumor-derived cytokines and growth factors (e.g., GM-CSF, IL-6, VEGF) drive the recruitment and reprogramming of myeloid cells into pro-tumoral phenotypes." (PMID 40821795, 2025). "Our study demonstrated that the metastasis of WT cells involves the horizontal transfer of the PIK3CAH1047R mutation in MT cell‐derived exosomes to fibroblasts, subsequently activating CAFs to release IL6, and promoting tumor cells' EMT in the primary foci." (PMID 40344411, 2025). "IL-6 drives tumor proliferation and angiogenesis and contributes to MDSC recruitment and therapy resistance (Dahmani and Delisle, 2018; Kim B.-G." (PMID 41244711, 2025). "Pro-inflammatory mediators such as TNF-α, IL-1β, and IL-6 not only stimulate angiogenesis but also alter tumor cell adhesion and infiltration, thereby enhancing metastatic behavior." (PMID 40557321, 2025). "Elevated levels of such common inflammatory factors as TNF-a, CRP, and IL-6 indicate increased tumor activity and higher malignancy, which can exacerbate the patient’s condition." (PMID 40621513, 2025). "CCA tumor cells drive M2 polarisation through cytokines such as IL‐6 and TGF‐β, acting via the IL‐6/STAT3 pathway." (PMID 41143064, 2025). "Serum IL-6 levels correlated with the expression of IL-6 in tumors and were thought to be involved in the suppression of tumor immunity in the TME." (PMID 39652104, 2025). "This cascade promotes tumor cell survival, proliferation, and the secretion of proinflammatory cytokines such as IL-6." (PMID 41465243, 2025). "Serum cytokines, such as TNF-α, IL-6, and IL-10, reflect inflammation and the tumor microenvironment." (PMID 41226541, 2025). "Several inflammatory mediators, including interleukins (IL-6, IL-8, IL-10), tumor necrosis factor (TNF), and chemokines (CXCL12, CXCR4), are implicated in tumor progression and the pathological inflammatory microenvironment of these tumors." (PMID 40433410, 2025). "Among the analysed cytokines, IL-1β (68.9%) and IL-6 (67.8%) showed the highest proportions of elevated expression, suggesting their prominent role in the tumour microenvironment." (PMID 41465261, 2025).
tumor (continued). "Dual inactivation of STK11 and KRAS genes alters the tumor secretome, resulting in increased secretion of IL-6." (PMID 41051525, 2025). "Exercise-induced acute release of IL-6 promotes antitumor adaptive immunity by inducing the migration of cytotoxic T cells to tumor-draining lymph nodes and tumor vasculature and stimulating lymphocyte trafficking." (PMID 40281902, 2025). "Galectin‐4 (Lgals4) is secreted from colonic epithelial cells and has likewise been shown to promote intestinal inflammation and tumor progression through stimulation of IL‐6." (PMID 39392222, 2025). "Cytokines such as TNF-α, IL-1β, IL-2, and IL-6 can enhance tumor growth, angiogenesis, metastasis, and invasion by promoting the survival and proliferation of tumor cells through activation of the NF-κB pathway." (PMID 40172365, 2025). "NF-κB-induced inflammatory cytokines, such as TNF-α, IL-1β, and IL-6, promote infiltration of tumor infiltrating macrophages (TAMs) and neutrophils into the tumor microenvironment, inhibiting cytotoxic T cell functions." (PMID 40169858, 2025). "IL-6, mainly derived from macrophages, mediates the interaction among cells and is a very important OSCC-promoting cytokine in the tumour microenvironment, which makes salivary IL-6 an increasingly powerful biomarker for the diagnosis of OSCC." (PMID 39911325, 2025). "Next, human peripheral blood NK cells were employed to further validate the impact of IL-6 within the tumor microenvironment on the expression of NKp30 and the cytotoxic function of these cells." (PMID 41254082, 2025). "Accumulating evidence has illustrated that the IL-6/IL-6R/STAT3 pathway plays a pivotal role in tumor occurrence and progression; however, the detailed mechanism has not yet been identified." (PMID 40779629, 2025). "In non-small cell lung cancer (NSCLC), FXR acts as a tumor-promoting driver, transactivating IL-6 and IL-6ST and activating the Jak2/signal transducer and activator of transcription 3 (STAT3) pathway, thereby enhancing metastatic potential and poor prognosis." (PMID 41339918, 2025). "T cells and monocytes secrete large amounts of pro-inflammatory cytokines, such as IL-2, IL-6, and TNFα, when co-cultured with TCam-2 cells, an effect which is significantly reduced when immune and tumor cells are separated by a Transwell insert." (PMID 40649953, 2025). "Such substances trigger the production of ROS, the recruitment and activation of immune cells to release inflammatory factors, such as tumor necrosis factor (TNF-α) and interleukin-6 (IL-6), thus promoting tumor metastasis." (PMID 40677396, 2025). "Laboratory findings have highlighted that targeting these pathways, specifically by inhibiting TNF-α and IL-6, can reduce tumour growth and improve clinical outcomes in preclinical models of HCC." (PMID 40544399, 2025). "LCN2 binds to SLC22A17 receptors on fibroblasts, activating STAT3, which further enhances fibroblast proliferation and secretion of MMPs and IL-6, reinforcing tumor growth and inflammation." (PMID 40472740, 2025). "IL-1β, in cooperation with IL-6 and low-dose TGF-β, biases Th17 cells toward a pathogenic profile that favors inflammation, angiogenesis, and tumor progression." (PMID 41181112, 2025). "Consistent with this, our experimental results indicate that HER2 + IBC tumour cells can mediate endothelial necroptosis through the PTN-NCL-TNF signaling axis to promote the expression of IL-6 and IL-8." (PMID 40624675, 2025). "The tumor microenvironment is a source of cytokines such as IL-6, IFN-γ, VEGF, and PDGF-BB, secreted mainly by tumor and immune cells." (PMID 40143164, 2025). "The activation of NF-κB is significantly increased in these cells, resulting in the secretion of cytokines such as IL6, TNFα, and IL1β, which subsequently promote cell proliferation and tumor viability." (PMID 40869207, 2025).